STX11 (syntaxin 11)
Description:
SNAREs (soluble N-ethylmaleimide-sensitive factor-attachment protein receptors) are essential proteins for intracellular membrane fusion. SNAREs localized on opposing membranes assemble to form a trans-SNARE complex, an extended, parallel four-helix bundle whose assembly releases energy that drives membrane fusion. The core SNARE complex typically consists of four alpha-helical domains, three from target membrane SNAREs (t-SNAREs) and one from a vesicle SNARE (v-SNARE). Syntaxin-11/STX11 is an atypical lipid-anchored t-SNARE that forms a SNARE complex with the t-SNARE SNAP23 and the v-SNARE VAMP8. This SNARE complex plays a critical role in the regulated exocytosis of cytotoxic granules by natural killer (NK) cells and cytotoxic T-lymphocytes. In macrophages, STX11 regulates stimulus-dependent vesicular transport of TLR4 from recycling endosomes to the plasma membrane by cooperating with SNAP23, thereby playing a critical role in microbial component recognition and the induction of innate and adaptive immunity (By similarity). In skeletal muscle satellite cells, STX11 cooperates with its cognate SNAREs VAMP4 and SNAP23 to facilitate CD36 vesicular transport from endosomes to the plasma membrane, an essential step in muscle regeneration (By similarity). In another proposed mechanism, STX11 may function as a regulator of the SNARE VTI1B on late endosomes to regulate trafficking from late endosomes to lysosomes.
Synonyms: FHL4; HLH4; HPLH4
Tractability: Antibody: UniProt places it where antibodies can reach, with high confidence; its Gene Ontology location is reachable by antibodies, with medium confidence. PROTAC: ubiquitination databases record sites on it; its protein half-life has been measured.
Gene: Protein-coding gene on chromosome 6 (144,149,970 to 144,191,939, forward strand). Ensembl gene ENSG00000135604.
Subcellular location: Cell membrane; Late endosome membrane
Gene Ontology:
Molecular function: fusogenic activity; protein binding; SNAP receptor activity; SNARE binding
Biological process: cytotoxic T cell degranulation; positive regulation of late endosome to lysosome transport; vesicle fusion; vesicle fusion to plasma membrane; exocytosis; synaptic vesicle fusion to presynaptic active zone membrane; intracellular protein transport; vesicle-mediated transport
Cellular component: immunological synapse; late endosome membrane; plasma membrane; recycling endosome membrane; SNARE complex; trans-Golgi network membrane; presynaptic active zone membrane; cytoplasm; membrane
Genetic constraint (gnomAD): Loss-of-function variants: 21 observed, 20.11 expected, observed/expected ratio (o/e) 1.04, 90% interval 0.74 to 1.5. The upper end of that interval is the gene's LOEUF score, 1.5, which puts it in group 6 of 6, group 1 being the genes least tolerant of losing a copy. Missense variants: 438 observed, 424.18 expected, observed/expected ratio (o/e) 1.03, 90% interval 0.95 to 1.12. Synonymous variants: 193 observed, 188 expected, observed/expected ratio (o/e) 1.03, 90% interval 0.91 to 1.16.
Gene-disease validity (ClinGen):
ClinGen rates the evidence that STX11 causes each of these diseases.
familial hemophagocytic lymphohistiocytosis 4 (autosomal recessive): Definitive.
Homologues: Orthologues: chimpanzee STX11 (99% identical), macaque STX11 (98% identical), rabbit STX11 (90% identical), guinea pig STX11 (89% identical), rat Stx11 (86% identical), mouse Stx11 (85% identical), pig STX11 (84% identical), dog STX11 (83% identical), tropical clawed frog stx11 (66% identical), zebrafish stx11a (50% identical), zebrafish stx11b.1 (43% identical), zebrafish stx11b.2 (36% identical), and 3 more. Paralogues in human: STX19 (37% identical), STX1B (33% identical), STX2 (31% identical), STX3 (31% identical), STX1A (30% identical), STX4 (27% identical), STX16 (20% identical), STX5 (18% identical), STX12 (17% identical), STX7 (16% identical), STX17 (13% identical), TSNARE1 (12% identical).